PNP (purine nucleoside phosphorylase)
Diseases named in the same sentence as PNP in open-access papers (continued):
Sharing a sentence is not in itself a finding about the gene and the disease.
malaria (3 papers, 2009 to 2025). Malaria is a serious and sometimes fatal disease caused by a parasite that commonly infects a certain type of mosquito which feeds on humans. "Purine nucleoside phosphorylase (PNP) is central to purine salvage mechanisms in Plasmodium parasites, the causative agents of malaria." (PMID 19575810, 2009). "In this study we have therefore extended studies of Plasmodium PNPs, firstly through a structural analysis of PNP from the second most prevalent human-specific malaria parasite, Plasmodium vivax (PvPNP)." (PMID 19575810, 2009). "Metabolic differences between humans and Aotus suggest PNP inhibition as anti-malaria therapy may be more effective in humans." (PMID 22096507, 2011). "Moreover, we apply metabolic tests to establish that PNP inhibition by BCX4945 blocks purine salvage, and demonstrate that polyamine synthesis is also reduced in the human malaria parasite." (PMID 22096507, 2011).
melanoma (3 papers, 2008 to 2015). A malignant, usually aggressive tumor composed of atypical, neoplastic melanocytes. "Two more of these target genes, NT5E and PNP, are candidate biomarkers for malignant melanoma." (PMID 26472186, 2015). "In B16 melanoma cells cell-specific expression of PNP and FCU1 was obtained using the melanoma-specific P4xTETP-promoter." (PMID 18402662, 2008).
ovarian carcinoma (3 papers, 2011 to 2022). A malignant neoplasm originating from the surface ovarian epithelium. "Thus, we have evaluated the prospective synergies between Purine Nucleoside Phosphorylase (PNP) mediated GDEPT and chemotherapeutics, docetaxel and carboplatin in multidrug resistant ovarian cancer cells." (PMID 21861932, 2011).
xanthinuria (3 papers, 2015 to 2025). A metabolic metabolic disorder characterized by excess urinary excretion of the purine base xanthine. "Mutations in enzymes in the purine metabolic pathway cause rare inborn errors of metabolism such as Lesch–Nyhan syndrome, purine nucleoside phosphorylase deficiency, and xanthinuria." (PMID 40991662, 2025). "Thus, the potential benefits of PNP inhibition in the treatment of human xanthinuria patients would need to be evaluated and weighed against the negative impacts on the immune system." (PMID 40991662, 2025).
anaemia (2 papers, 2023 to 2025). "Here, we show for the first time that in adults with SCD, PNP levels are higher than in their age‐ and race‐matched HbAA controls; these levels are associated negatively with anaemia, and positively with LDH and other hemolytic parameters." (PMID 41469749, 2025).
Ataxia (2 papers, 2020 to 2022). Ataxia refers to impaired coordination of voluntary muscle movement. "Non-infectious dysfunction, particularly neurological abnormalities such as ataxia and spasticity, are frequently reported in PNP-deficient patients and in mice lacking the PNP enzyme." (PMID 32695102, 2020). "Cells from a patient with a mutated ataxia telangiectasia gene and from a patient with absent PNP activity, who had suffered from ataxia and delayed motor skills, demonstrated markedly decreased survival following irradiation." (PMID 32695102, 2020).
ataxia telangiectasia (2 papers, 2013 to 2020). Ataxia-telangiectasia is the association of severe combined immunodeficiency (affecting mainly the humoral immune response) with progressive cerebellar ataxia. "As expected, lymphoblastoid cells obtained from a patient with a mutated ataxia telangiectasia gene and a patient with a complete absence of PNP activity were particularly sensitive to irradiation, resulting in a significantly reduced (p < 0.001) SF compared to controls." (PMID 32695102, 2020). "In contrast, cells established from patients II.1 and II.2 had SF that were not statistically different from PNP-proficient controls but significantly increased compared to cells from patients with ataxia telangiectasia and absent PNP activity." (PMID 32695102, 2020). "The survival of lymphoblastoid B cells from 2 partial PNP-deficient patients after irradiation was similar to that of PNP-proficient cells and markedly higher than the survival of cells from a patient with absent PNP activity or a patient with ataxia telangiectasia." (PMID 32695102, 2020).
bladder cancer (2 papers, 2019 to 2025). "It regulates prothymosin-α (PTMA) and purine nucleoside phosphorylase (PNP) in bladder cancer and PIK3CA in NSCLC (Non-small cell lung carcinoma)." (PMID 30862091, 2019). "Similarly, knockdown of PNP in bladder cancer cells resulted in a reduction of cell viability and apoptosis." (PMID 41502507, 2025).
eosinophilia (2 papers, 2022 to 2023). "On the other hand, the Sm + PNP and Sm + MIX group presented a negative regulation of this eosinophilia, but also showed a decreased of granulomas and eggs in the hepatic tissue." (PMID 37111413, 2023).
immune deficiency disorders (2 papers, 2020 to 2024). "Purine nucleoside phosphorylase (PNP) deficiency is one of the very rare types of immune deficiency disorders inherited in an autosomal recessive (AR) manner." (PMID 39845221, 2024). "DNA isolated from the patient's PBMCs and tested with a commercial panel (Blueprint Genetics®) for 232 genes associated with primary immunodeficiency (PID) revealed a homozygous variant c.769C>G in exon 6 of the PNP gene." (PMID 32695102, 2020).
Lesch–Nyhan disease (2 papers, 2016 to 2022). "Among them are Lesch–Nyhan disease, later shown to be caused by deficient hypoxanthine-guanine phosphoribosyltransferase (HPRT) activity, adenosine deaminase (ADA) deficiency and purine nucleoside phosphorylase (PNP) deficiency." (PMID 35955904, 2022).
neuroblastoma (2 papers, 2021 to 2022). Neuroblastoma (NB) is the most common solid, extracranial childhood tumor. "The IC50 values against GR, Waldenstrom macroglobulinemia (WM), purine nucleoside phosphorylase (PNP), LAN-5, and Gaslini Institute-LI-neuroblastoma (GILIN) cell lines were found to be 23, 27, 29, 16, and 19 μM, respectively." (PMID 36362950, 2022).
Nijmegen breakage syndrome (2 papers, 2013 to 2020). Nijmegen breakage syndrome is a rare genetic disease presenting at birth with microcephaly, dysmorphic facial features, becoming more noticeable with age, growth delay, and later-onset complications such as malignancies and infections. "The method, which includes KREC analysis to assess potential B-cell lymphopenia, allows for additional identification of patients with XLA, Nijmegen breakage syndrome, and purine nucleoside phosphorylase (PNP) deficiency." (PMID 33178177, 2020).
parasitemia (2 papers, 2023 to 2024). "Blood samples from an infected untreated monkey showed increased PNP activity as the parasitemia increased, while treated animals showed approximately 98% PNP inhibition during the treatment period." (PMID 38837364, 2024). "Purine nucleosidephosphorylase (PNP) is a well-known moleculartarget with potential therapeutic applications in the treatment ofT-cell malignancies and/or bacterial/parasitic infections." (PMID 37134237, 2023).
peripheral T cell lymphomas (2 papers, 2019 to 2023). "This study evaluated the efficacy and safety of forodesine, a novel purine nucleoside phosphorylase inhibitor, in patients with relapsed peripheral T cell lymphomas." (PMID 29974231, 2019).
schistosomiasis (2 papers, 2016 to 2023). An infectious disease caused by parasitic trematodes of the genus Schistosoma that colonize human blood vessels and release eggs that can cause granulomatous reactions leading to acute (swimmer's itch or acute schistosomiasis syndrome) or chronic disease. "Therefore, immunotherapy with the recombinant enzymes of S. mansoni HGPRT and PNP might contribute to the control and reduction of the pathophysiological aspects of schistosomiasis, helping to decrease the morbidity associated with the infection in murine model." (PMID 37111413, 2023). "Purine nucleoside phosphorylase (PNP) from Schistosoma mansoni (schistosomiasis) and humans have been immobilized which could be used as an alternative to the usual coupled assay for the selective screening of ligands." (PMID 28070446, 2016). "The present study evaluated the effects of the recombinant enzymes of S. mansoni Hypoxanthine-Guanine Phosphoribosyltransferase (HGPRT), Purine Nucleoside Phosphorylase (PNP) and the MIX of both enzymes in the immunotherapy of schistosomiasis in murine model." (PMID 37111413, 2023).
T cell deficiency (2 papers, 2014 to 2025). "The T cell deficiency associated with PNP inactivation is managed in the clinic with HSCT alongside other treatments." (PMID 40519286, 2025). "Pharmacological PNP inhibition was found to selectively eradicate T cell leukemia cells in vitro, thus mirroring the observations of T cell deficiency in patients with PNP-linked SCID." (PMID 40519286, 2025). "The observations of T cell deficiency in PNP-deficient patients made by Giblett and colleagues have been confirmed by other groups who have expanded the catalog of altered immune phenotypes associated with PNP deficiency in humans." (PMID 40519286, 2025). "Similarly, while mice with PNP deficiency recapitulate the T cell deficiency observed in humans lacking PNP, mice experience a less severe phenotype, often lacking neurological symptoms." (PMID 40519286, 2025).
B cell deficiencies (1 paper, 2019). "These conditions include severe forms of B cell deficiencies such as XLA, with an approximate incidence of 1:100,000, but also some patients with late-onset adenosine deaminase deficiency (ADA) and purine nucleoside phosphorylase (PNP) deficiencies." (PMID 33072998, 2019).
breast tumors (1 paper, 2023). "Likewise, both RT-qPCR quantified RNA and protein abundance of NT5C2 was significantly increased, but with significant suppression of PNP level in TC than TM area of breast tumors." (PMID 37532694, 2023).
bronchiectasis (1 paper, 2020). Segmental, irreversible dilation of the bronchial tree resulting in the accumulation of secretions which leads to obstruction. "A third patient, with “late-onset” PNP deficiency with very low PNP activity, suffered from recurrent respiratory infections resulting in bronchiectasis and was treated with intravenous immunoglobulins until HSC transplantation at 13 years of age." (PMID 32695102, 2020).
bronchogenic carcinoma (1 paper, 2025). A lung carcinoma arising from the bronchial epithelium. "In addition, PNP activity was found to be high in the lymphocytes of patients with bronchogenic carcinoma and non-Hodgkin lymphomas." (PMID 41502507, 2025).
central precocious puberty (1 paper, 2021). "The function of AK1, NME1-NME2 and PNP in central precocious puberty needs further research to clarify the relationship between nitrogenous base metabolism and CPP pathogenesis." (PMID 34748517, 2021).
chickenpox (1 paper, 2020). A contagious childhood disorder caused by the varicella zoster virus. "Another PNP-deficient patient was healthy until 6 years of age when she developed a severe autoimmune cytopenia followed by sinusitis and a fatal chickenpox episode at 11 years of age." (PMID 32695102, 2020).
chronic granulomatous disease (1 paper, 2022). Chronic granulomatous disease (CGD) is a rare primary immunodeficiency, mainly affecting phagocytes, which is characterized by an increased susceptibility to severe and recurrent bacterial and fungal infections, along with the development of granulomas. "Genetic defects in PNP, PIK3CD, STAT1, ISG15, IL2RB, GS3, DNASE2 and genes associating chronic granulomatous disease were found among 7 of the 25 patients who underwent genetical testing." (PMID 35964089, 2022).
colon cancer (1 paper, 2025). "It was previously reported that PNP expression increased with the advancement of colon cancer stages." (PMID 41502507, 2025).
colorectal cancer (1 paper, 2019). A primary or metastatic malignant neoplasm that affects the colon or rectum. "In our study, we found PNP expression to be significantly downregulated by GS treatment in HCT 116 cells indicating that it forms one of the potential targets of GS in this colorectal cancer cells." (PMID 31581454, 2019).
cystitis (1 paper, 2026). Inflammation of the urinary bladder. "This review will focus on an emerging therapy for cystitis, namely 8-aminoguanine (8-AG), which inhibits the enzyme purine nucleoside phosphorylase (PNPase)." (PMID 42303425, 2026).
endometriosis (1 paper, 2018). The growth of functional endometrial tissue in anatomic sites outside the uterine body. "A previous study applied parallel gene expression profiling using high-density oligonucleotide microarrays to investigate the regulation of gene expression in the endometrium, and reduction of PNP expression was found in endometriosis patients, which supports our hypothesis." (PMID 29712562, 2018).
esophageal cancer (1 paper, 2021). A primary or metastatic malignant neoplasm involving the esophagus. "Patients with stage I esophageal cancer had significantly higher expression of CPS1 (p = 0.003), PNP (p = 0.007), SERPINB8 (p = 0.042) and EHD1 (p = 0.046)." (PMID 33828156, 2021).
Granuloma (1 paper, 2023). A compact, organized collection of mature mononuclear phagocytes, which may be but is not necessarily accompanied by accessory features such as necrosis. "The results of this study show that the use of the recombinant enzymes from S. mansoni HGPRT, PNP and MIX significantly decreased the eggs/gram of feces, in the liver and, consequently, the number of granulomas." (PMID 37111413, 2023).
haemolytic anaemia (1 paper, 2019). "Based on the presence of haemolytic anaemia, T lymphocyte defect and increase in urinary orotic acid, purine nucleoside phosphorylase (PNP)-deficiency was suspected." (PMID 31118063, 2019).
head and neck cancer (1 paper, 2023). A primary or metastatic malignant neoplasm affecting the head and neck. "Our studies provide the scientific foundation necessary to improve PNP prodrug cleavage and advance a new treatment for head and neck cancer." (PMID 36253876, 2023).
head and neck squamous cell carcinoma (1 paper, 2023). A squamous cell carcinoma that arises from any of the following anatomic sites: lip and oral cavity, nasal cavity, paranasal sinuses, pharynx, larynx, and salivary glands. "Such strategies have been tested clinically with encouraging results against head and neck squamous cell carcinoma (HNSCC) using a modified Escherichia coli purine nucleoside phosphorylase (PNP) gene and replication deficient adenovirus." (PMID 36253876, 2023).
hemorrhagic cystitis (1 paper, 2024). Inflammation of the bladder resulting in bloody urine. "The purine nucleoside phosphorylase inhibitor 8-aminoguanine reduces pain and prevents damage in a rat model of hemorrhagic cystitis." (PMID 38271096, 2024).
hepatocellular carcinoma (1 paper, 2018). A malignant tumor that arises from hepatocytes. "The purpose of this study is to generate an ultrasonic nanobubble (NB)-mediated purine nucleoside phosphorylase (PNP)/fludarabine suicide gene system for the treatment of human hepatocellular carcinoma (HCC)." (PMID 29718963, 2018).
HIV-1 infection (1 paper, 2022). The type species of lentivirus and the etiologic agent of acquired immunodeficiency syndrome (AIDS). "For example, SAMHD1, a dNTP-degrading phosphohydrolase and intracellular enzyme that restricts HIV-1 infection of myeloid cells, along with the purine nucleoside phosphorylase PNP affect survival rates of dGuo-exposed cells." (PMID 35355997, 2022).
influenza (1 paper, 2025). An acute viral infection of the respiratory tract, occurring in isolated cases, in epidemics, or in pandemics; it is caused by serologically different strains of viruses (influenzaviruses) designated A, B, and C, has a 3-day incubation period, and usually lasts for 3 to 10 days. "Therefore, our study revealed the bridging role of PNP and PNP-mediated purine salvage in influenza, and the anti-influenza effect of PNP deficiency was contributed by its dual inhibition on viral replication and host inflammation." (PMID 40517177, 2025). "Collectively, our results clearly demonstrated the potential of PNP as an anti-influenza host target, with PNP inhibitors being efficient to combat IAV." (PMID 40517177, 2025). "Our study sheds new light on a “two-for-one” strategy by targeting purine salvage in combating IAV-related pathology, suggesting PNP as a potential novel anti-influenza host target." (PMID 40517177, 2025). "PNP is a crucial enzyme in purine salvage and responsible for the phosphorylation of inosine and deoxyinosine into hypoxanthine, as well as guanosine and deoxyguanosine into guanine, which prompted us to unveil the role of purine salvage during influenza." (PMID 40517177, 2025).
invasive breast carcinoma (1 paper, 2025). A carcinoma that infiltrates the breast parenchyma. "Transcriptomics data of 2509 patients with invasive breast carcinoma were re-analyzed by dividing the cohort according to PNP expression into patients with high PNP expression and others with low PNP expression according to the mRNA level of PNP." (PMID 41502507, 2025).
liver cancer (1 paper, 2022). An epithelial or non-epithelial malignant neoplasm that arises from the liver. "An intriguing finding is that similar alterations in gene expression have been described in a molecular subtype of liver cancer developed by Peruvian patients originating from the Central Andes20,41, which might suggest a role for PNP in promoting the disease in the region." (PMID 35941193, 2022).
liver fibrosis (1 paper, 2023). "The enzyme HGPRT could reduce the physiopathological aspects that lead to related morbidity, such as liver fibrosis and positive modulation for IL-4 and IgE expression, while the enzyme PNP showed effect on the worm itself, reducing the parasitic load and number of eggs." (PMID 37111413, 2023).
lupus erythematosus (1 paper, 2020). An autoimmune, connective tissue chronic inflammatory disorder affecting the skin, joints, kidneys, lungs, heart, and the peripheral blood cells. "Moreover, a PNP polymorphism was identified in a systemic‐lupus erythematosus patient and linked to enhanced type I IFN induction." (PMID 31608988, 2020).
neutropenia (1 paper, 2017). A decrease in the number of neutrophils found in the blood. "She had neutropenia, pan-lymphocytopenia, and hypogammaglobulinemia with low plasma urate and erythrocyte PNP activity." (PMID 28674683, 2017).
osteonecrosis (1 paper, 2023). A none disease characterized by death of bone tissue due to a lack of blood supply. "It was experimentally verified that both PNP and SLC2A1 were significantly downregulated in the peripheral blood of SONFH patients, as well as in the hormonal osteonecrosis samples, which was consistent with the results of our bioinformatics analysis." (PMID 36979852, 2023).
pancreatic cancer (1 paper, 2022). "PNP inhibitors additionally provide a novel approach for therapeutic TLR7 activation for use as a vaccine adjuvant or for treatment of immunologically cold malignancies with upregulated PNP expression, such as pancreatic cancer." (PMID 35653193, 2022).
periodontal disease (1 paper, 2022). "Another enzyme, the purine nucleoside phosphorylase (PNP), which catalyzes the reversible phosphorolysis of purine nucleosides, i.e., inosine and guanosine into hypoxanthine and guanine, respectively, has resulted to be upregulated in gingival crevicular fluid in periodontal disease." (PMID 35887132, 2022).
pneumonia (1 paper, 2021). An acute, acute and chronic, or chronic inflammation focally or diffusely affecting the lung parenchyma, caused by an infection in one or both of the lungs (by bacteria, viruses, fungi, or mycoplasma.). "We conducted subgroup analyses among patients with (ATB+) and without (ATB−) antibiotics and with (PNP+) or without (PNP−) pneumonia at the time of inclusion." (PMID 33675432, 2021).